HOXC6 (homeobox C6)
Diseases named in the same sentence as HOXC6 in open-access papers (continued):
Sharing a sentence is not in itself a finding about the gene and the disease.
cancer (47 papers, 2009 to 2025). A tumor composed of atypical neoplastic, often pleomorphic cells that invade other tissues. "In the context of invasion and metastasis, HOXC6 emerges as a key player implicated in the aggressive behaviour of cancer cells, including their propensity to invade surrounding tissues and disseminate to distant sites such as lymph nodes." (PMID 41477365, 2025). "High expression of genes such as HOXB5, HOXC11, HOXA13, HOXD13, HOXA6, and HOXC6 in certain cancers is linked to poor overall survival (OS)." (PMID 39980564, 2025). "Many HOX genes, especially HOXB7 and HOXC6, have higher expression and lower overall survival in specific cancers and are predicted as risk factors." (PMID 39980564, 2025). "Several previous studies have shown that high expression of HOXC6 is associated with poor prognosis in cancer patients." (PMID 38012642, 2023). "Homeobox C6 (HOXC6), a member of the homeobox family that encodes highly conserved transcription factors, plays a vital role in various carcinomas." (PMID 27081081, 2016). "However, the underlying mechanisms of the role of HOXC6 in cancer are not fully understood." (PMID 35008435, 2021). "Elevated expression of HOXB7 and HOXC6 potentially facilitates cancer progression, leading to the accumulation of cancer cells." (PMID 39980564, 2025). "The homeobox protein HOXC6 represents one such factor that exhibits cancer-specific upregulation and functionally contributes to malignant cell expansion." (PMID 40574852, 2025). "Studies have consistently shown that dysregulated HOXC6 expression correlates with increased invasiveness and metastatic potential across different cancer types, including OSCC." (PMID 41477365, 2025). "Leveraging powerful platform, BEST, we conducted an in-depth analysis of HOXC6’s functional expression patterns across diverse cancer types." (PMID 40574852, 2025). "HOXC6 modulates EMT through the TGF-B/Smad pathway in this cancer type, as HOXC6 knockdowns have decreased TGF-B1, TGFB2, Smad4, and p-Smad2 expression." (PMID 39858044, 2025). "HOXC6 (homeobox protein Hox-C6) is an overexpressed TF with a very high oncogenic potential in NSCLC progression as it is a regulator of genes related to cancer cells proliferation and metastasis." (PMID 36101460, 2022). "Homeobox C6 (HOXC6) is a transcription factor that plays a role in the malignant progression of various cancers." (PMID 35008435, 2021). "In this study, we used microRNA (miRNA) regulatory networks to identify key regulatory interactions responsible for HOXC6-mediated cancer progression." (PMID 35008435, 2021). "It has been demonstrated that HOXC6 has value in the diagnosis of cancer development, progression, or response to therapy, thus serving as a novel biomarker of various cancers." (PMID 35008435, 2021). "HOXA13, HOXD13 and HOXC6 were reported to promote cancer progression in CRC, and HOXB13 was reported to suppress tumors in CRC." (PMID 34950145, 2021). "In CRC, HOXA13, HOXD13 and HOXC6 were reported to promote cancer progression, and HOXB13 was reported to suppress tumors." (PMID 34950145, 2021). "Remarkably, Oncomine dataset showed upregulation of HOXC6 mRNA in the GC compared to other cancer types." (PMID 32745141, 2020). "Although they compared HOXC6 expression in cancer tissues with that in neighboring normal tissues, the potentially crucial candidate gene selection was not based on actual screening methods such as sequencing." (PMID 32745141, 2020). "We found that the expression of HOXC6 mRNA was upregulated with the progression of cancer, which was validated by quantitative real time PCR and RNA in-situ hybridization." (PMID 32745141, 2020). "Since these phenotypes are directly related to the development and progression of cancer, HOXC6 emerges as an oncogene in ESCC." (PMID 30886783, 2019). "Wound healing and Matrigel assays were performed to assess the effect of HOXC6 on the migration and invasion of cancer cells." (PMID 30886783, 2019).
cancer (continued). "This is consistent with the results of other reports focused on the function of HOXC6 in cancers other than ESCC." (PMID 30886783, 2019). "In other types of cancers, HOXC6 has also been shown to have the capacity to regulate these cancer-related genes." (PMID 30993034, 2019). "Fourth, HOXC6 can upregulate the expression of genes critical for the development and progression of various cancers." (PMID 30993034, 2019). "The three target genes were each significantly downregulated in cancer tissues and expression of each one correlated inversely with that of HOXC6." (PMID 24213107, 2011). "HOXB7 and HOXC6 may serve as potential targets for cancer treatment and the development of targeted compounds in the future." (PMID 39980564, 2025). "We hypothesize that the expression of HOXB7 and HOXC6 follows a normal distribution trend during cancer cell occurrence and development." (PMID 39980564, 2025). "HOXC6, an important transcription factor, is involved in multiple cancers." (PMID 35488304, 2022). "Additionally, we also found in an in vitro study that cancer cells with decreased HOXC6 expression had markedly increased sensitivity to anticancer drugs, such as cisplatin and paclitaxel." (PMID 35008435, 2021). "Our results suggested that miR-188-5p and its regulated target genes could affect the development of HOXC6-mediated cancer by regulating cellular mechanisms." (PMID 35008435, 2021). "Given that HuR, identified as a member of RBPs, has been implicated in the progression of cancers, we speculated that BBOX1‐AS1 might regulate HOXC6 expression via HuR, too." (PMID 32515533, 2020). "The phenotypic effects of HOXC6 may be mediated by genes that have been previously reported to be involved in the progression of cancer." (PMID 30993034, 2019). "However, to our surprise, we found that HOXC6 exerted its effects on the transcription patterns of cancer in a cell-context-dependent manner." (PMID 30886783, 2019). "The aberrant expression of HOXC6 has been reported in many cancer types; however, the mechanisms underlying the function of this gene in cancer cells have not been fully elucidated." (PMID 30886783, 2019). "HOXC6 has also been found to be highly expressed in several cancers." (PMID 30993034, 2019). "HOXC6 is a homeodomain-containing transcription factor that is highly expressed in several human cancers; however, its role in NSCLC remains unknown." (PMID 30993034, 2019). "HOXC6 is highly expressed in many cancer types, including ESCC." (PMID 30886783, 2019). "Inprostate cancer cells, HOXC6 knockdown reduced proliferation by inducing apoptosis." (PMID 27081081, 2016). "Furthermore, HOXC6 plays a key role in the regulation of multiple cellular signaling pathways during tumorigenesis, so it is considered as a novel biomarker for various cancers." (PMID 36176299, 2022). "Our findings suggest that miR-188-5p exerts significant cancer-promoting effects in HOXC6-mediated cancer progression by inhibiting FOXN2 expression; thus, miR-188-5p might be a potential prognostic marker and therapeutic target for HOXC6-overexpressing cancers." (PMID 35008435, 2021). "Additionally, after the patients were classified into groups, as control, EGC, and AGC based on the comparative analysis, the results showed that there was a gradual increase in the levels of HOXC6 mRNA levels with cancer progression (p<0.0001, Kruskal-Wallis test)." (PMID 32745141, 2020). "This suggests that HOXC6 may be a critical factor in cancer development." (PMID 30886783, 2019). "In addition, HOXC6 deregulation has been detected in several cancer types." (PMID 29348394, 2018). "Moreover, HOXC6 deregulation has been detected in several cancer types." (PMID 27081081, 2016). "HOXB7 and HOXC6 were positively correlated with TMB in most cancers, and HOXB7 was strongly correlated with TMB in ACC, HNSC, PAAD, and STAD, and HOXC6 was strongly correlated with TMB in COAD, LGG, MESO, and PRAD (R>0.2)." (PMID 39980564, 2025).
cancer (continued). "Immediately, we analyzed the expression of the top three genes, which tie for first place (HOXC6, APCDD1, and ASCL2) in multiple cancer types to explore possible roles of the genes in carcinogenesis." (PMID 35774798, 2022). "Nevertheless, the roles of HOXC6, SERPINE1, FABP4, SCG2, and CALB2 in tumorigenesis, cancer immunity, and ICB treatment are poorly understood." (PMID 35836930, 2022). "Although the expression of certain HOX genes is often reported as being characteristic of specific cancers, for example, HOXC4 and HOXC6 in prostate cancer, generally the majority of the 39 HOX genes are significantly upregulated." (PMID 35080776, 2022). "From our best research, HOXC6, SLC2A4, VIP, CD1A, STC2, and OLFM2 are related to cancer progression." (PMID 35711425, 2022). "Third, HOXC6 enhanced the migration and invasion of NSCLC cells, which are fundamental hallmarks of cancer." (PMID 30993034, 2019). "HOXC6 is a member of the HOX family, and its aberrant expression has been verified in a variety of cancers, such as prostate, breast, nasopharyngeal carcinoma, gastric, and ovarian cancers." (PMID 30886783, 2019). "Higher positive expression rate of HOXC6 protein was observed in CC tissues and HOXC6 was related to TNM stage, lymphatic metastasis, cancer types, primary lesion diameter, and histological grade of CC." (PMID 30559605, 2018). "Likewise, the buccal mucosa-derived H157 (RRID: CVCL_2468) cancer cell lines showed overexpression of HOXA10, HOXC6, HOXC9, HOXC10 and HOXD11 which was consistent with the cancer of the buccal mucosa." (PMID 35710803, 2022). "However, the mechanism by which HOXC6 involved in tumorigenesis and cancer progression has not been elucidated yet." (PMID 29348394, 2018). "Finally, the mutually exclusive overexpression between AR, HOXC6 and NKX2-2 is preserved across various tissues and cancers, suggesting that mutual exclusivity may represent an intrinsic characteristic of driver TFs during tumorigenesis." (PMID 28397780, 2017).
HOXC6 also shares sentences with these, for which no sentence is quoted: acute lymphoblastic leukaemia (2 papers); squamous cell carcinoma (2); adrenocortical tumours (1); anaplastic large cell lymphoma (1); colitis (1); colon adenocarcinoma (1); congenital heart disease (1); Ewing sarcoma (1); Hepatitis (1); Hutchinson-Gilford progeria syndrome (1); invasive breast carcinoma (1); kidney tumors (1); leiomyoma (1); lymphoma (1); melanoma (1); metastatic colorectal cancer (1); mouth neoplasms (1); non-small cell lung carcinoma (1); rectal adenocarcinoma (1); renal carcinoma (1); Sjögren’s syndrome (1); stomach adenocarcinoma (1); T-cell lymphoma (1); thyroid carcinoma (1).